CRYAB (crystallin alpha B)
Description:
May contribute to the transparency and refractive index of the lens. Has chaperone-like activity, preventing aggregation of various proteins under a wide range of stress conditions. In lens epithelial cells, stabilizes the ATP6V1A protein, preventing its degradation by the proteasome (By similarity).
Synonyms: HspB5; CRYA2; CMD1II; CTPP2; CTRCT16; HEL-S-101; MFM2; MFM2A; MFM2B
Tractability: Small molecule: a structure with a bound ligand is known; a high-quality ligand is known. Antibody: UniProt places it where antibodies can reach, with high confidence; its Gene Ontology location is reachable by antibodies, with medium confidence; the Human Protein Atlas places it where antibodies can reach. PROTAC: ubiquitination databases record sites on it; a small molecule that binds it is known.
Gene: Protein-coding gene on chromosome 11 (111,908,564 to 111,923,722, reverse strand). Ensembl gene ENSG00000109846.
Subcellular location: Cytoplasm; Nucleus; Secreted; Lysosome
Subcellular location (Human Protein Atlas): Cytosol; Plasma membrane
Pathways (Reactome):
Cellular responses to stimuli: HSF1-dependent transactivation
Gene Ontology:
Molecular function: amyloid-beta binding; identical protein binding; protein binding; protein homodimerization activity; protein-containing complex binding; structural molecule activity; cytoskeletal protein binding; microtubule binding; structural constituent of eye lens
Biological process: cellular response to gamma radiation; negative regulation of amyloid fibril formation; negative regulation of apoptotic process; negative regulation of DNA-templated transcription; negative regulation of intracellular transport; negative regulation of protein-containing complex assembly; protein stabilization; regulation of programmed cell death; muscle contraction; protein folding; protein refolding; response to heat; microtubule polymerization or depolymerization; negative regulation of cell growth; negative regulation of reactive oxygen species metabolic process; response to estradiol; response to hydrogen peroxide; stress-activated MAPK cascade
Cellular component: cytoplasm; cytosol; extracellular exosome; extracellular region; nucleus; plasma membrane; protein-containing complex; lysosome; nucleoplasm; actin filament bundle; axon; cardiac myofibril; cell surface; contractile muscle fiber; dendritic spine; I band; M band; mitochondrion; perikaryon; synaptic membrane; Z disc
Genetic constraint (gnomAD): Loss-of-function variants: 9 observed, 13.31 expected, observed/expected ratio (o/e) 0.68, 90% interval 0.41 to 1.18. The upper end of that interval is the gene's LOEUF score, 1.18, which puts it in group 5 of 6, group 1 being the genes least tolerant of losing a copy. Missense variants: 183 observed, 232.89 expected, observed/expected ratio (o/e) 0.79, 90% interval 0.7 to 0.89. Synonymous variants: 93 observed, 90.08 expected, observed/expected ratio (o/e) 1.03, 90% interval 0.87 to 1.23.
Homologues: Orthologues: chimpanzee CRYAB (99% identical), macaque CRYAB (99% identical), dog CRYAB (98% identical), rabbit CRYAB (98% identical), mouse Cryab (98% identical), pig CRYAB (97% identical), rat Cryab (97% identical), guinea pig CRYAB (96% identical), tropical clawed frog cryab (68% identical), zebrafish cryaba (59% identical), zebrafish cryabb (57% identical), Drosophila melanogaster l(2)efl (40% identical), and 15 more. Paralogues in human: CRYAA (53% identical), HSPB6 (45% identical), HSPB1 (44% identical), HSPB2 (36% identical), HSPB8 (30% identical), HSPB7 (23% identical), HSPB3 (21% identical), HSPB9 (18% identical).
Diseases named in the same sentence as CRYAB in open-access papers:
CRYAB is named in the same sentence as 175 diseases in open-access papers, as found by Europe PMC text mining. Sharing a sentence is not in itself a finding about the gene and the disease. The quoted sentences say what the papers report.
cardiomyopathy (32 papers, 2009 to 2025). A disease of the heart muscle or myocardium proper. "Mutations in desmin or CRYAB lead to common molecular defects known as desminopathies that involve impaired mitochondrial morphology leading to cardiomyopathies, as a result of desmin aggregation or reduction in desmin and CRYAB29–31." (PMID 40480980, 2025). "Previously documented mutations in CRYAB have been linked to the development of various cardiomyopathies via the disruption of ionic bridges critically involved in the molecular chaperone function of CRYAB." (PMID 40141027, 2025). "On the other hand, similarities in preamyloid oligomers were found in αB-crystallin (CryAB)-mutation-associated cardiomyopathy and AD." (PMID 38903751, 2024). "Collectively, these seminal works identified CRYAB as a potential hotspot for cardiomyopathy-inducing gene mutations." (PMID 37435054, 2023). "UPS impairment has also been demonstrated in cardiomyopathy caused by mutations in desmin or αB-crystallin (CryAB) leading to accumulation of desmin in skeletal and cardiac muscle." (PMID 36111332, 2022). "In 6 of 10 cases of sporadic DCM and in single cases of RCM and HCM, we found de novo mutations in genes previously associated with cardiomyopathy (CRYAB, DSP, MYH7, SCN5A, TNNC1, and TTN)." (PMID 32013205, 2020). "CRYAB has been implicated in stress-inducible translocation, antiapoptosis, remodeling of the cytoskeleton, cardioprotection and inheritable cardiomyopathy in humans." (PMID 24489661, 2014). "Dominant mutations in the alpha-B crystallin (CryAB) gene are responsible for a number of inherited human disorders, including cardiomyopathy, skeletal muscle myopathy, and cataracts." (PMID 23818860, 2013). "Cardiomyopathy caused by mutations in CryAB is correlated with the presence of cytoplasmic protein aggregates containing CryAB and a number of other proteins." (PMID 23818860, 2013). "CRYAB (αB-crystallin) is expressed in many tissues and yet the R120G mutation in CRYAB causes tissue-specific pathologies, namely cardiomyopathy and cataract." (PMID 23530264, 2013). "In addition to modulating the calcineurin-NFAT axis, CRYAB has been implicated in a variety of pathologic processes associated with cardiomyopathies, including autophagy, apoptosis and redox balance." (PMID 37435054, 2023). "We identified further genes that regulate the development of trabeculation (NKX2-5, TBX20, HAND2, NRG1, NOTCH1 and DTNA) and those with evidence of involvement in cardiomyopathies (CRYAB and RIT1 (ARHGEF2))." (PMID 39567769, 2024). "In the section of cardiomyopathy, reductive stress-inducing factors including heat shock protein 27 (Hsp27 or HspB1), alpha-B crystalline (CryAB or HspB5), and Nrf2 were specifically elaborated." (PMID 32566086, 2020). "It is reported that during aging and during the progression of cardiomyopathy, both CryAB and its phosphorylation are elevated." (PMID 32566086, 2020). "In 8/12 probands (66.7%), we found likely causative variants in known cardiomyopathy genes (TTN, DSP, SCN5A, TNNC1, TPM1, CRYAB, and MYH7), which were confirmed as de novo (six DCM, one HCM, and one RCM case)." (PMID 32013205, 2020). "In 8 (66.7%), we found de novo variants in known cardiomyopathy genes (TTN, DSP, SCN5A, TNNC1, TPM1, CRYAB, MYH7)." (PMID 32013205, 2020). "Based on the findings of the current study, we propose a novel mechanism by which CVB3 infection targets CryAB contributing to virus-induced cardiomyopathy." (PMID 29088822, 2017). "The current study addresses a novel function and mechanism of CryAB dysregulation in the pathogenesis of viral myocarditis/cardiomyopathy." (PMID 29088822, 2017). "This mutation induces CryAB protein aggregation and in mice, overexpression of R120G mutant CryAB induces cardiomyopathy, whereas overexpression of its wild-type counterpart does not." (PMID 22536506, 2012). "Here we would like to focus on three cardiomyopathy-related factors: Hsp27, CryAB, and Nrf2." (PMID 32566086, 2020).
cardiomyopathy (continued). "Similarly, the overexpression of ATG7 ameliorates signs of DES (desmin)‐related cardiomyopathy in mice expressing the R120G mutant of CRYAB (crystallin, alpha B), whereas the heterozygous loss of Becn1 accelerates heart failure under the same pathological setting." (PMID 34459017, 2021). "Across multiple mouse models of desmin-related cardiomyopathies, MLF2 was consistently enriched in protein aggregates and interacted with key proteins involved in protein quality control, including αB-crystallin (CryAB)." (PMID 41590846, 2025). "In this study, we observed rare P/LP/VUS+ variants in 4 genes associated with cardiomyopathy (MYH7, CRYAB, SCN5A, and MYBPC3) in individuals without a history of MI or HF and with extensive myocardial fibrosis indicated by CMR." (PMID 35265679, 2022).
breast carcinoma (26 papers, 2010 to 2023). "Studies have shown that the high expression of CRYAB is associated with tumor development and is a marker of poor prognosis for head and neck cancer, and breast cancer." (PMID 36552262, 2022). "CRYAB was also associated with various cancers, including breast cancer, prostate cancer and lung cancer, and CRYAB protein was significantly related to different kinds of signaling pathways, such as inflammation, oxidative stress and apoptosis." (PMID 34362387, 2021). "CRYAB was involved in a variety of signaling pathways implicated in breast cancer, lung cancer, prostate cancer, and ovarian cancer." (PMID 31991631, 2020). "In metaplastic breast cancer, CRYAB was found to be highly expressed and associated with brain metastasis, and silencing the CRYAB gene using RNA interference technology significantly reduced tumor invasion and metastasis ability." (PMID 31152111, 2019). "According to a database called METABRIC24,25, CRYAB expression level was tended to increase after chemotherapy treatment across breast cancer patients and in the TNBC patients." (PMID 36899050, 2023). "In breast cancer, CRYAB is a marker for aggressive behavior in triple-negative basal-like breast cancer and mammary metaplastic carcinoma and its overexpression is associated with the presence of lymph nodal and brain metastasis and relapse." (PMID 36624493, 2023). "CRYAB has been reported to regulate angiogenesis in retinal pigment epithelial, breast cancer and gastric cancer cells; however, to our knowledge, no reports have indicated that CRYAB expression in mature CMs promotes angiogenesis both in vitro and in vivo." (PMID 37679796, 2023). "Our approach can deliver convergence for archival datasets as well as those from recent treatment and patient cohorts and can align HSP27 and CRYAB expression to important clinical-pathological features of breast cancer." (PMID 35235182, 2021). "Our data suggest that HSP27 and CRYAB have different epichaperome influences in breast cancer, but more importantly evidence the value of a cluster analysis that considers their coexpression." (PMID 35235182, 2021). "Here we use cluster analysis to assess the relative and joint expression of CRYAB and HSP27 associated with breast cancer in the Cancer Genome Atlas." (PMID 35235182, 2021). "CRYAB has been reported to be a marker of poor prognosis in breast cancer and has oncogenic potential, although this is open to discussion." (PMID 35235182, 2021). "This targeted approach identified three different patient populations based upon their combined HSP27 and CRYAB expression levels within the breast cancer samples." (PMID 35235182, 2021). "Our cluster analysis of the Cancer Genome Atlas for co-expression of HSP27 and CRYAB in breast cancer patients identified three patient groups based on their expression level combination (high HSP27 + low CRYAB; low HSP27 + high CRYAB; similar HSP27 + CRYAB)." (PMID 35235182, 2021). "CRYAB is highly expressed in a variety of cancers, among which includes breast cancer, lung cancer, colorectal cancer, thyroid carcinoma, and glioblastoma." (PMID 32595729, 2020). "The role of CRYAB gene (Alpha B-crystallin HSPB5) is controversial in cancer, its expression has been associated with aggressive breast cancer subtypes." (PMID 29954368, 2018). "Given the recent study linking αB-crystallin to breast cancer brain metastasis, we examined the relationship between CRYAB expression and brain metastasis as the first distant relapse." (PMID 27656679, 2015). "Recently, there has been found a correlation between the phosphorylation of CRYAB with apoptosis in breast cancer cells." (PMID 22350622, 2012). "This study could be the first of many that unpicks previously contradictory conclusions in relation to the role and impact of HSP27 and CRYAB in breast cancer." (PMID 35235182, 2021).
breast carcinoma (continued). "A recent study identified CRYAB as part of a gene cluster associated with good prognosis despite its significant association with the clinical-pathological parameters of ER−/PR− and HER2−, a breast cancer patient group with poor prognosis." (PMID 35235182, 2021). "Statistical analyses of our data suggest that CRYAB and HSP27 both contribute to breast cancer, but their epichaperome influences are different." (PMID 35235182, 2021). "Our results further expand this consensus by demonstrating CRYAB and HSP27 are dependent upon each other, but also have potentially different influences in breast cancer." (PMID 35235182, 2021). "Our assessment of the variable expression of HSP27 and CRYAB in the TMA24 is that each sHSP and their combinations affect the breast cancer epichaperome differently." (PMID 35235182, 2021). "Finally, to examine whether αB-crystallin (gene name: CRYAB) was also involved in human breast cancer development, using the public database, we reviewed the mRNA expression of CRYAB in normal breast and invasive breast cancer tissues in Gene Expression Omnibus (GEO) (Expression Profile GDS3324)." (PMID 31443698, 2019). "We clustered the breast cancer dataset within TCGA with respect to HSP27 and CRYAB expression." (PMID 35235182, 2021). "The coassembly of HSP27 and CRYAB has so far not been considered as an important variable in the transcriptional and omic analyses of breast cancer cohorts." (PMID 35235182, 2021). "These previous studies compared expression levels between cancerous and non-cancerous samples to identify the same basic characteristic for the different breast cancer groups represented in the TCGA cohort, namely raised HSP27 expression and lowered CRYAB expression." (PMID 35235182, 2021). "CRYAB is a member of the small heat shock protein family, and many studies have confirmed that CRYAB plays an important role in a variety of tumours, such as OSCC, colorectal cancer, breast cancer, and hepatocellular carcinoma." (PMID 32117620, 2020).
glioma (17 papers, 2004 to 2024). A benign or malignant brain and spinal cord tumor that arises from glial cells (astrocytes, oligodendrocytes, ependymal cells). "In summary, we discovered an association between plasma CRYAB levels and the presentation of preoperative seizures in glioma." (PMID 38971757, 2024). "Our study revealed that within the terminal differentiation stage of glioma tissue, a subpopulation of oligodendroglial cells exhibited the highest expression of CRYAB, which was associated with prognosis and confirmed by in vitro experiments." (PMID 38274814, 2023). "In certain types of cancers, including breast cancer, prostate cancer, and glioma, overexpression of the CRYAB gene is associated with malignancy." (PMID 38274814, 2023). "This study aimed to investigate plasma levels of CRYAB as a biomarker for predicting epilepsy seizures among patients with glioma." (PMID 38971757, 2024). "Studies have consistently reported elevated levels of CRYAB in GBM specimens, establishing the role of CRYAB in glioma genesis." (PMID 38971757, 2024). "Our findings reveal that decreased plasma levels of CRYAB are observed in glioma patients with pre-operative seizures in comparison to those without pre-operative seizures." (PMID 38971757, 2024). "This study investigates the potential of Alpha B crystallin protein (CRYAB) plasma levels as a predictive biomarker for epilepsy seizures in glioma patients." (PMID 38971757, 2024). "Tumor necrosis factor-alpha (TNF-α) and Interleukin-1 beta (IL-1β) can induce the production of the small heat shock protein, CRYAB (HspB5) in U373 glioma cells, and U373-secreted exosomes." (PMID 37373314, 2023). "The studies of the Kore' group (2014) revealed that CRYAB (HSPB5) was upregulated in the exosomes after inflammation response in glioma cells potentially induced the antiapoptotic response to applied treatment (Kore and Abraham, 2014)." (PMID 34177409, 2021). "We also analyzed the expression of CRYAB (alpha-B crystallin) as this protein was described to be elevated up to 22-fold in IDH1-mutant gliomas." (PMID 33925547, 2021). "A potential link between CRYAB, NOTCH1, and BMP pathways is also supported by diffuse low-grade glioma RNA profiles in the TCGA database, showing a significant correlation between CRYAB, BMP2, and HEY2 expression." (PMID 33925547, 2021). "Moreover, they discovered that K+ induced CRYAB expression and that CRYAB expression in rat C6 glioma cells protect these cells against the insult of elevated extracellular K+ on the glioma cells." (PMID 36430241, 2022). "In addition to these well-established glioma markers, we identified several other proteins that have never been associated with glioma biology including (e.g., SLC1A3, CLU, LGALS3BP, ANGPTL2, CRYAB and ITGB8)." (PMID 25360666, 2014). "TNF-α and Interleukin-1 β (IL-1β) induce in glioma cells the production of the heat shock protein known as crystallin alpha B (CRYAB, also indicated as HspB5)." (PMID 39194524, 2024). "Pro-inflammatory IL-1β and TNF-α cytokines result in changes in the exosomal proteome of U373 glioma cells, significantly increasing the levels of CRYAB (HspB5), a heat shock protein with anti-apoptotic activity." (PMID 33227947, 2020). "Major discriminator between high-grade and low-grade tumors included CRYAB, IPYR, TPIS, PEA15, PSD13, GFAP, IDH3A, 6PGL, PHP14, KCRB as overexpressed in low-grade gliomas; HCD2, HBA, HBD as overexpressed in high-grade GBM." (PMID 25050814, 2014). "PADI4 and CRYAB proteins, identified among the most abundant proteins exclusive of ND GBM pre-surgery saliva and classified as proteins elevated in glioma, could have a potential role as disease biomarkers." (PMID 39684695, 2024).